INS (insulin)
Diseases named in the same sentence as INS in open-access papers (continued):
Sharing a sentence is not in itself a finding about the gene and the disease.
Obesity (continued). "Alterations in insulin signaling in humans are associated with a vast number of risk factors or co-morbid conditions including obesity, cardiovascular disease, and intermittent hypoxia conditions, such as obstructive sleep apnea." (PMID 25541690, 2014). "The endocrinological and/or biochemical milieu associated with obesity, operating through a functional state such as insulin resistance, can create a hostile intraovarian or intrauterine environment for the oocytes or embryos." (PMID 25763394, 2014). "The study’s purpose was to use recombinant human growth hormone (rhGH) as a physiologic probe to assess the effects of reversing obesity-related GH deficiency on body composition, cardiovascular risk markers, and insulin resistance." (PMID 25435886, 2014). "In order to explore possible mechanism underlying inhibition of placental mTOR signaling in obesity, we examined the activation of energy, insulin, and inflammatory pathways, which are upstream modulators of mTOR." (PMID 24744907, 2014). "We therefore used an unbiased approach (unbiased, distance-based hierarchical cluster analysis) to recognize adipokine patterns associated with parameters of obesity, glucose metabolism, insulin sensitivity and inflammation." (PMID 24968098, 2014). "Irisin has since been linked to a variety of disorders, including obesity, anorexia nervosa, insulin sensitivity, nonalcoholic fatty liver disease and chronic kidney disease." (PMID 25369206, 2014). "In contrast, in ZF rats, a model of obesity with a mutation in the leptin receptor gene, basal insulin secretion was already high compared with the control, but significant GIIS occurred." (PMID 25373904, 2014). "Increased macrophage infiltration was initially observed in white adipose tissue (WAT) and has been considered a hallmark of obesity-induced tissue inflammation, which deteriorates insulin sensitivity and glucose metabolism." (PMID 24911652, 2014). "While the T-bet knockout mice were expected to have increased insulin sensitivity, the finding that they were more obese, with increased visceral adiposity, was surprising, as obesity and insulin resistance are typically co-associated." (PMID 25157251, 2014). "Obesity is associated with increased inflammation, elevated blood lipids and glucose levels, and insensitivity to insulin, which contribute to the initiation and propagation of cardiovascular and other chronic diseases." (PMID 25574495, 2014). "Included in the effects of obesity is its association with a chronic low-grade state of inflammation as well as elevations in blood glucose and alterations in serum factors such as insulin, leptin, adiponectin, and insulin-like-growth factor (IGF)-1." (PMID 24804677, 2014). "One of the most common causes of chronic liver disease, nonalcoholic fatty liver disease (NAFLD), is strongly associated with obesity and dysregulated insulin action in the liver." (PMID 24944601, 2014). "Since insulin and leptin are strongly associated with increases in obesity, it is plausible that there is a cross over from peripheral circulation to the reproductive tract." (PMID 24885899, 2014). "Both salivary immunoreactive insulin and salivary ghrelin have been associated with T2D and obesity, and were included in our analysis." (PMID 24915044, 2014). "Mice carrying one or more Adcy3Jll mutant alleles are protected from high fat diet-induced obesity, are more active, and have lower circulating leptin and insulin levels." (PMID 25329148, 2014). "The potential relationship linking vitamin D to metabolic homeostasis in obesity was substantiated by the observed association between vitamin D and insulin secretion, as well as HDL cholesterol levels." (PMID 24618074, 2014). "Collectively, these results suggest that IFNT improves obesity-associated glucose metabolismand insulin sensitivity." (PMID 24905566, 2014).
Obesity (continued). "Increased ceramide levels in muscle have also been imputed as a cause of diminished insulin signaling to Akt and impaired glucose transport in obesity and T2DM." (PMID 26237474, 2014). "Patients with T2DM and/or obesity have a significantly increased risk of heart attack and stroke when compared to people who have a normal insulin sensitivity and a normal weight." (PMID 25528960, 2014). "In central nervous system (CNS), IR causes obesity, since in humans, appetite is increased by the action of insulin in the CNS and the current data indicate that neuronal insulin signaling is required for both body weight control and glucose homeostasis." (PMID 25069836, 2014). "A question remains to be answered is how reducing insulin signaling, which is associated with various aging-associated metabolic and cardiovascular diseases such as obesity, type 2 diabetes, and hypertension, extends lifespan." (PMID 24474199, 2014). "We demonstrated that obesity is associated with increased levels of C-peptide, leptin, insulin, GLP-1, PYY, and glucagon." (PMID 25309773, 2014). "A number of studies have revealed that cardiovascular risk factors, such as dyslipidemia, hypertension, obesity, fasting BG, increased insulin and body iron stores are correlated." (PMID 24926364, 2014). "High–fat (HF) diet-induced obesity and insulin insensitivity are associated with inflammation, particularly in white adipose tissue (WAT)." (PMID 25170916, 2014). "On the other hand obesity is usually associated with insulin resistance and with increased levels of circulating insulin that can in turn promote cell proliferation and survival." (PMID 25360116, 2014). "On the other hand, altered cell metabolism, as observed during obesity and insulin resistant conditions, is becoming increasingly associated with cancer development and progression." (PMID 25360116, 2014). "Obesity was also associated with increased levels of leptin, insulin, glucagon, GLP-1, PYY, and C-peptide in overweight and obese chimpanzees." (PMID 25309773, 2014). "By the way, impaired insulin stimulated uptake of glucose associated with impaired vasodilatation has been shown to be early manifestations in insulin resistant models of obesity." (PMID 24966877, 2014). "BMI is used as a screening tool for overweight and obesity, and high BMI-for-age values are related to clinical risk factors for chronic diseases including hyperlipidemia, elevated insulin, and high blood pressure." (PMID 25110666, 2014). "In particular, excessive fat accumulation in the liver caused by obesity in general dysregulates insulin action in the liver, leading to insulin resistance." (PMID 25299819, 2014). "Increased HISS action is associated with delayed onset of obesity and maintained direct insulin action." (PMID 26237598, 2014). "Adiponectin is an abundant anti-inflammatory cytokine which is secreted by adipose tissue and has been implicated to play a major role in insulin sensitivity and obesity." (PMID 24693420, 2014). "Obesity in rats caused by alterations in hypothalamic arcuate nucleus and impairs leptin and insulin signaling in this region resulting in hyperleptinemia and hyperinsulinemia." (PMID 25030027, 2014). "Excess of saturated fatty acids in the diet has been associated with obesity, leading to systemic disruption of insulin signaling, glucose intolerance, and inflammation." (PMID 25332517, 2014). "Aging is characterized by decline in cellular function and is associated with obesity, inflammation, energy metabolism, and insulin resistance." (PMID 25239873, 2014). "Obesity is associated with insulin resistance, which alters the levels of plasma glucose, insulin and insulin-like growth factor-1 (IGF-1)." (PMID 24396438, 2014). "Previous studies have demonstrated roles for DUSP family members in the development of obesity, and obesity-associated inflammation and insulin sensitivity." (PMID 25375135, 2014).
Obesity (continued). "Expression of apelin in adipocytes is shown to be increased in mouse models of obesity associated with hyperinsulinemia, and apelin levels paralleled plasma insulin levels during fasting and refeeding of mice." (PMID 24475149, 2014). "Tissue inflammation is now recognized as a major cause of impaired insulin sensitivity in obesity and has been observed in all classical insulin target tissues including fat, liver and muscle." (PMID 25244011, 2014). "Recent studies have pointed to chronic inflammation in insulin target tissues, such as muscle, liver, and adipose tissue, as one of the causal links between obesity and insulin resistance." (PMID 25333972, 2014). "Our results demonstrate that detrimental effects on both metabolic (blood glucose, insulin sensitivity) and proinflammatory (cytokine expression) responses caused by diet-induced obesity are exacerbated by testosterone depletion." (PMID 25224590, 2014). "Obesity is associated with increased serum and seminal insulin and leptin in a cohort of male participants." (PMID 24885899, 2014). "AT dysfunction has been considered a key initiating factor and the main source of inflammatory signaling in obesity-associated metabolic alterations, along with the resulting insulin resistant state." (PMID 25400333, 2014). "We and others have recently reported that elevated vaspin serum concentrations are associated with obesity and impaired insulin sensitivity in humans." (PMID 23370777, 2013). "Imbalances in whole body glucose and insulin homeostasis are also closely linked to the trend of increased obesity." (PMID 23675313, 2013). "The details of obesity as a causal factor of IR are complex; awareness of the molecular aspects of insulin signaling will facilitate its understanding." (PMID 24892324, 2013). "Although we cannot determine from this study why obesity predisposition was associated with insulin sensitivity in AA and not EA, this ethnic/race difference likely relates to greater insulin responsiveness in AA." (PMID 23298367, 2013). "The decreased sensitivity to insulin leads to an increased requirement for insulin and is often associated with obesity in which metabolic disturbances are marked in insulin-target organs, such as the liver, muscle, and adipose tissues." (PMID 23691524, 2013). "Despite the fact that chronic low-grade inflammation is directly linked with the consumption of high-carbohydrate diets, sucrose is one of the important elements in HFD which is the leading cause of obesity, high blood sugar, and insulin resistance." (PMID 24302970, 2013). "Chronic treatment of exendin-4, a long acting GLP-1 analogue, in a rodent obesity model results in improved insulin sensitivity and loss of body weight." (PMID 24386644, 2013). "The DHT-induced rat PCOS model used in the current study is associated with androgen-induced obesity and reduced insulin sensitivity even when maintained on a normal chow diet." (PMID 23690868, 2013). "Obesity leads to an inflammatory state which is linked to reduced insulin sensitivity and expression of GLUT4 in adipose tissue, skeletal muscle, and heart." (PMID 23691518, 2013). "Transgenic increase of maternal n-3/n-6 PUFA reduces obesity-related inflammation, which is associated with improved maternal insulin sensitivity and reduced placental and fetal hepatic lipid accumulation." (PMID 23825686, 2013). "Although less common, the R80Q variant should be subjected to further analysis to evaluate its influence on insulin sensitivity, proinsulin conversion and the risk of developing obesity, similarly to the effect of the N221D (rs6232) SNP." (PMID 23383060, 2013). "Deletion of IKKβ in myeloid cells reduced macrophage-mediated inflammation and improved obesity-associated systemic and hepatic insulin sensitivity." (PMID 23964268, 2013).
Obesity (continued). "Obesity, as a disorder, is a well-known condition which can place individuals at a significantly elevated risk for impaired insulin action and various metabolic abnormalities such as hypertension, dyslipidemia, and a reduction in glucose tolerance." (PMID 23472169, 2013). "Weight management programs can attenuate T2D risk by reducing obesity and improving insulin sensitivity; however the long-term success of this approach is not optimal." (PMID 23675368, 2013). "Human KLF14 controls many essential genes that are linked to a range of metabolic conditions including obesity, cholesterol, insulin and glucose levels." (PMID 23557393, 2013). "Sirtuins have been shown to regulate several obesity-associated metabolic changes including regulation of adiponectin secretion, insulin secretion and sensitivity, plasma glucose levels, regulation of oxygen consumption, and mitochondrial capacity." (PMID 23819063, 2013). "NLRP3 inflammasome plays a substantial role in sensing obesity-associated inducers of caspase-1 activation and therefore regulates the magnitude of the inflammation and its downstream effects on insulin signaling in different organs, as reported here later." (PMID 23843683, 2013). "Because obesity is associated with impaired insulin sensitivity, we tested the trend association of alcohol or wine intake with histologic types stratified by BMI (<30 vs ≥30 kg/m2)." (PMID 23339562, 2013). "Adiponectin functions to counter the metabolic program associated with obesity and hyperleptinemia by modulating glucose metabolism, increasing fatty acid oxidation and insulin sensitivity, and decreasing production of inflammatory cytokines." (PMID 23967401, 2013). "It has been demonstrated in rodents and humans that chronic inflammation characterized by macrophage infiltration occurs mainly in adipose tissue or liver during obesity, in which activation of immune cells is closely associated with insulin sensitivity." (PMID 23964268, 2013). "Recent studies have associated the compromised insulin signaling in patients with obesity, prediabetes, and T2DM with altered intermediary metabolism of fats and amino acids." (PMID 24252331, 2013). "Decreased insulin sensitivity in cardiovascular tissues is an underlying abnormality in obesity, hypertension, and T2DM." (PMID 24369540, 2013). "Another potential link is that obesity, being associated with metabolic syndrome, results in increased circulating levels of insulin and insulin-like growth factor (IGF), which are associated to carcinogenesis." (PMID 23819063, 2013). "For vaspin, we and others have reported that elevated vaspin serum concentrations are associated with obesity and impaired insulin sensitivity in humans." (PMID 23370777, 2013). "There are clear interactions between obesity, insulin, and IGFs which compound their effects on cancer risk." (PMID 23983688, 2013). "We suggest that the higher fasting glucose levels in overweight and obese groups occurred in the early normal glycometabolism stage, and were mainly caused by the reduced insulin sensitivity associated with increased obesity." (PMID 24137224, 2013). "In this study, decreases in insulin and NO concentration were associated with lower obesity index in those rats with excess iron in their modified diet." (PMID 23179349, 2013). "At about 2 months of age, the KK mouse manifested moderate obesity due to hyperphagic, which was associated with insulin resistance, compensatory hyperinsulinemia, and islet cell hyperplasia." (PMID 23671868, 2013). "They investigated in fact interactions between p66Shc and signalling cascades (mTOR/S6 kinase) triggered by insulin and nutrients in leptin-deficient LepOb/Ob mice, a genetic model of obesity and IR." (PMID 23606925, 2013). "In this study, the effects of clozapine on mitochondrial function and inflammation in insulin responsive and obesity-associated cultured cell lines were examined." (PMID 23527073, 2013).
Obesity (continued). "Risk for obesity differs with ethnicity/race and is associated with insulin sensitivity (SI), insulin responsiveness, and dietary glycemic load (GL)." (PMID 23298367, 2013). "We also discuss its potential role for a variety of insulin resistant and pre-diabetic states, obesity, metabolic abnormalities associated with HIV disease, gestational diabetes, cancer, and neuroprotection." (PMID 23415113, 2013). "The CARDIA study found that active commuting was inversely associated with BMI, obesity, triglyceride level, blood pressure, and fasting insulin and positively associated with high density lipoprotein (HDL) cholesterol." (PMID 23776412, 2013). "Our results suggest that processes associated with these factors contribute only minimally, at least for the obesity risk, once insulin has been taken into account." (PMID 23806173, 2013). "In this study, in addition to SKNSH neuroblastoma cells, we examined the effect of clozapine on insulin responsive cell types and cells associated with obesity: fat, muscle, liver and inflammatory cells." (PMID 23527073, 2013). "This mutation has been shown to be associated with obesity, hyperinsulinaemia, decreased glucose tolerance, increased insulin sensitivity, hyper-lipidaemia, and decreased plasma free fatty acids." (PMID 23750248, 2013). "Hyperinsulinemia and hyperleptinemia indicates the insulin and leptin resistance, which is associated with obesity, dyslipidemia, and glucose intolerance." (PMID 24312343, 2013). "At present, it is believed that M2 macrophages contribute to maintain insulin sensitivity, while obesity causes a switch to M1 polarization that enhances systemic insulin resistance through the secretion of inflammatory cytokines." (PMID 23964268, 2013). "Development of diet-induced obesity in WT mice was associated with increased plasma levels of insulin, leptin, cholesterol and triglycerides as compared to Cox6a2−/− mice." (PMID 23460811, 2013). "For these reasons, in addition to human neuroblastoma cells, the present study examines the effects of clozapine on insulin responsive and obesity-associated cell types: cultured mouse fat, muscle, liver and inflammatory cell lines." (PMID 23527073, 2013). "It is well established that this population with severe obesity and poor glycaemic control is challenging to manage successfully due to the risk of aggravating their obesity with intensification of insulin therapy 50,51." (PMID 23061470, 2013). "Clozapine damages mitochondria and promotes inflammation in insulin responsive cells and obesity-associated cell types." (PMID 23527073, 2013). "Cyclin D3-deficient mice are protected from diet-induced obesity, exhibit reduced adipocyte size, and exhibit increased sensitivity to insulin." (PMID 23355973, 2013). "PTP-1B-deficient mice are more sensitive to insulin and are more resistant to diet-induced obesity than wild-type mice." (PMID 23442260, 2013). "n-3 PUFAs intake has also been associated with beneficial effects related to obesity, insulin sensitivity, and the reduction of inflammatory markers." (PMID 22980234, 2012). "The long recognized association between cardiovascular disease and obesity became clearer in 1988 when Reaven consolidated the concept proposing that insulin resistance with compensatory hyperinsulinemia was a fundamental pathogenetic mechanism." (PMID 22462579, 2012). "Further, experimental and genetic interventions that block the hypothalamic NF-κB signaling reversed hypothalamic insulin and leptin resistance and was associated with reduced food intake and weight loss in the high-fat-induced obesity." (PMID 22844271, 2012). "This study examines prevalence of obesity and cardiovascular risk factors such as cholesterol level, fasting insulin, fasting glucose, adiponectin, high blood pressure and looks at the factors associated with obesity in children at age 11–13." (PMID 22693553, 2012).